ERCC1 (ERCC excision repair 1, endonuclease non-catalytic subunit)
Diseases named in the same sentence as ERCC1 in open-access papers (continued):
Sharing a sentence is not in itself a finding about the gene and the disease.
colon carcinoma (21 papers, 2004 to 2024). "We next consider the extent of the field defects that are deficient in Pms2 and Ercc1 in colon segments that were resected, due either to the presence of colon cancer or due to large tubulovillous adenomas." (PMID 22494821, 2012). "In conclusion, our data suggested that KRAS mutation is a predictor of oxaliplatin sensitivity in colon cancer cells by ERCC1 downregulation." (PMID 23209813, 2012). "Overall, our findings suggest that KRAS mutation is a predictor of oxaliplatin sensitivity in colon cancer cells by the mechanism of ERCC1 downregulation." (PMID 23209813, 2012). "Our study shows that KRAS mutation is a predictor of oxaliplatin sensitivity in colon cancer cells by ERCC1 downregulation." (PMID 23209813, 2012). "The ERCC1 Codon 118 polymorphism is associated with different mRNA levels and high levels have been associated with a shorter overall survival for colon carcinoma patients treated with platinum-based chemotherapy." (PMID 19077243, 2008). "We were also interested in whether deficiencies in protein expression of Pms2, Ercc1, Xpf or Ku86 could be biomarkers of colon cancer risk within biopsies taken during colonoscopies." (PMID 22494821, 2012). "This suggests that colon cancers tend to arise in field defects that are deficient in DNA repair and that deficiencies in protein expression of Pms2, Ercc1 and Xpf are frequent early, and often coordinated, steps in progression to colon cancer, as well as further progression within cancers." (PMID 22494821, 2012). "This instability would be expected to enhance progression to colon cancer by causing a mutator phenotype, and could also account for the presence of the cells doubly deficient in Pms2 and Ercc1 (or Xpf) we observed in field defects associated with colon cancer." (PMID 22494821, 2012). "For example, increased TOPO1 and ERCC1 expression, HER2/neu amplification, and KRAS mutation rates in rectal cancer compared with right- and left-sided colon cancer were reported." (PMID 34188197, 2021). "In colon cancer ERCC1 expression has been studied as a marker for sensitivity to combined therapies of 5-FU with other drugs, such as cisplatin, and different reports indicate that a high expression of ERCC1 is associated with poor prognosis." (PMID 32244885, 2020). "Initial in silico screening identified a compound binding to the XPA-interacting pocket of ERCC1 that enhanced the UV sensitivity of human colon cancer cells by 2-fold, but had a weaker effect on cisplatin sensitivity." (PMID 28903417, 2017). "In the multivariate analysis, higher ERCC1-19q13 copy numbers were significantly associated with longer survival and TTR, but only in patients with colon tumors." (PMID 24144331, 2013). "ERCC1-19q13 gain was more frequently observed in rectal tumors (24/71 – 33.8%) than colon tumors (17/81 – 21.0%)." (PMID 24144331, 2013). "Taken together, these findings suggest that ERCC1-19q13 copy number increases occur in both colon and rectal tumors, but are only related to better prognosis in patients with colon tumors." (PMID 24144331, 2013). "The identified inhibitors significantly sensitized colon cancer cells to UV radiation indicating a strong inhibition of the ERCC1-XPA interaction." (PMID 23272099, 2012). "Substantially reduced protein expression of Pms2, Ercc1 and Xpf occurred in field defects of up to 10 cm longitudinally distant from colon cancers or TVAs and within colon cancers." (PMID 22494821, 2012). "Our findings reveal a new validated ERCC1-XPA inhibitor that significantly sensitized colon cancer cells to UV radiation indicating a strong inhibition of the ERCC1-XPA interaction." (PMID 23272099, 2012). "Likewise, the expression of ERCC1 is a significant predictive biomarker for patients with colon cancer undergoing neoadjuvant or adjuvant oxaliplatin-based chemotherapy." (PMID 36497002, 2022).
colon carcinoma (continued). "Similarly, Zhang and colleagues found in a colon cancer cell line, knocking down ERCC1 protein expression increased the response to cells to CPT-11 in combination with ABT-888 as measured by γ-H2AX phosphorylation." (PMID 25774912, 2015). "ERCC1-19q13 gain was significantly associated with longer survival (multivariate analysis, HR: 0.45, 95% CI: 0.20-1.00, p = 0.049) in patients with colon tumors, but not rectal tumors." (PMID 24144331, 2013). "There were also 32 tissue samples obtained at 1-10 cm from colon cancers (removed during resection) that were cut as triplicates and immunostained for Pms2, Ercc1 and Xpf, as well as 38 additional tissue samples obtained at 1-10 cm from colon cancers that were immunostained for Ku86." (PMID 22494821, 2012). "The levels of expression of DNA repair proteins Pms2, Ercc1 and Xpf were evaluated by immunohistochemistry (IHC) in sequential tissue sections from individuals who never had a colonic neoplasm, and thus are at low risk of colon cancer." (PMID 22494821, 2012). "In a previous study, ERCC1, PARP1, and AQP1 were identified as poor prognostic biomarkers for colon cancer at stages II-III." (PMID 37234985, 2023). "In conclusion, ERCC1-19q13 gain occurs in a significant fraction of CRC tumors, whereas deletion of this locus occurs infrequently and was only observed in colon tumors." (PMID 24144331, 2013). "ERCC1-19q13 copy number gains occur frequently in stage III CRC and influences survival in patients with colon tumors." (PMID 24144331, 2013). "Similarly, ERCC1-19q13 gain was significantly associated with longer survival (HR: 0.45, 95% CI: 0.20-1.00, p = 0.049) in colon tumors, whereas only a non-significant trend was observed with TTR as endpoint in the colon subgroup (HR: 0.42, 95% CI: 0.16-1.07, p = 0.07)." (PMID 24144331, 2013). "Due to the important role of ROS in cancer and the indication that Pms2 and Ercc1 are specific targets of ROS, we directed our attention to evaluating whether Pms2 and Ercc1 (and Xpf, the pairing partner of Ercc1) were systematically reduced in progression to colon cancer." (PMID 22494821, 2012). "In this analysis, higher ERCC1-19q13 copy numbers and ERCC1-19q13/CEN-2 ratios were significantly associated with longer survival and TTR in patients with colon tumors, but not in patients with rectal tumors." (PMID 24144331, 2013). "This non-significant finding may be attributed to the low number colon tumor specimens (17 of 81 specimens) harboring an ERCC1-19q13 gain." (PMID 24144331, 2013). "Multivariate analysis, performed adjusting for age and gender, revealed significant relationships between higher ERCC1-19q13 copy numbers and ERCC1-19q13/CEN-2 ratios and longer survival and TTR in patients with colon tumors, but not rectal tumors." (PMID 24144331, 2013).
cervical carcinoma (20 papers, 2008 to 2025). A carcinoma arising from either the exocervical squamous epithelium or the endocervical glandular epithelium. "As an example of these previous statements, a study by Du underlined that ERCC1 has been identified as a very promising biomarker for cervical cancer." (PMID 38275866, 2024). "Soares’ group noted that ERCC1 rs3212986 is the risk factor for late gastrointestinal toxicity in cervical cancer patients." (PMID 39596349, 2024). "A growing amount of case-control studies have focused on making an investigation of the association between ERCC1 rs11615 polymorphism and cervical cancer susceptibility." (PMID 36245993, 2022). "It is worth noting that low ERCC1 expression is also associated with poor prognosis in cervical cancer patients." (PMID 36245993, 2022). "Excision repair cross-complementation group 1 (ERCC1) (the DNA repair gene) is a gene associated with platinum sensitivity and has been proposed as a novel biomarker of cervical cancer over the years." (PMID 36713431, 2022). "In this comprehensive review, there were three studies reporting the association between ERCC1 polymorphisms and the risk of cervical cancer." (PMID 36713431, 2022). "This meta-analysis is aimed at making an investigation into the correlation between ERCC1 rs11615 polymorphism and the risk of cervical cancer." (PMID 36245993, 2022). "The majority of the included studies suggested that the ERCC1 served as a pro-oncogenic factor in both early-stage and advanced cervix cancer due to high expression of ERCC1 has been found to be associated with poor survival of the patients." (PMID 36713431, 2022). "The results of the present study along with those from our previous ones, BCL2, HER-2, CD133, CAIX and ERCC1 were revealed to have significant associations with cervical cancer prognosis." (PMID 34350111, 2021). "On the contrary, MDR1 G2677 T and ERCC1 N118 N genetic polymorphisms examined in the study appeared to influence the median PFS of patients with metastatic or recurrent cervical cancer." (PMID 28659181, 2017). "Earlier in vitro studies have linked cisplatin resistance to the expression of ERCC1 mRNA in cell lines of cervical cancers." (PMID 23259415, 2012). "In a murine xenograft model, upregulated ERCC1 expression is associated with radioresistance in tumors derived from cervical carcinoma cells." (PMID 23259415, 2012). "Analysis of ERCC1 polymorphism suggests that it might serve as a valuable tool for predicting the likelihood of developing cervical cancer and the potentially hazardous side effects of therapy." (PMID 38275866, 2024). "Experimental studies suggested that the biological effects exerted by ERCC1 in cervical cancer might be mediated by its associated genes and affected signaling pathways." (PMID 36713431, 2022). "Second, ERCC1 polymorphisms might also play roles in predicting the risk of cervical cancer and the toxicities that underwent cisplatin treatment, but whether these polymorphisms function in patients’ survival has not been elucidated." (PMID 36713431, 2022). "ERCC1 polymorphism analyses demonstrated that ERCC1 might be a useful tool for predicting the risk of cervical cancer and the treatment-related toxicities." (PMID 36713431, 2022). "In brief, this meta-analysis put forward a conclusion that the ERCC1 rs11615 polymorphism increases cervical cancer susceptibility, especially in the Chinese populations, while TT genotype may have a higher risk." (PMID 36245993, 2022). "Experimental studies indicated that the biological effects exerted by ERCC1 in cervical cancer might be mediated by its associated genes and affected signaling pathways (i.e., XPF, TUBB3, and." (PMID 36713431, 2022). "ERCC1 polymorphism detection might be a useful tool for predicting the risk of cervical cancer and the toxicities that underwent cisplatin treatment." (PMID 36713431, 2022).
cervical carcinoma (continued). "Additionally, a case-control study showed that low expression of ERCC1 was closely related to a significantly increased risk for cervical cancer." (PMID 36713431, 2022). "Molecular mechanisms underlying the effects of ERCC1 in cervical cancer." (PMID 36713431, 2022). "In consequence, based on existing case-control studies, we carried out this new meta-analysis, aiming to elucidate the correlation between ERCC1 rs11615 polymorphism and cervical cancer susceptibility and better predict the occurrence and development of cervical cancer in clinical practice." (PMID 36245993, 2022). "Among these eligible studies, thirteen studies were clinical trials reporting the ERCC1 expression and cervix cancer, three studies were clinical studies reporting the ERCC1 polymorphism and cervix cancer, and three experimental studies reporting the molecular roles of ERCC1 in cervix cancer." (PMID 36713431, 2022). "In addition to the early stage of uterine cervix cancer, ERCC1 expression was also found to be associated with the prognosis of advanced cervix adenocarcinoma." (PMID 36713431, 2022). "Therefore, we hypothesized that ERCC1 rs11615 polymorphism might play a role in cervical cancer susceptibility and prognosis." (PMID 36245993, 2022). "Even though, detection of ERCC1 polymorphism might be a useful method for implementing strategies when choosing a proper treatment for a patient so as to reduce the toxicities or improve the treatment response rates in cervical cancer women." (PMID 36713431, 2022). "In addition, studies have shown that individuals with reduced ERCC1 expression may have a higher risk of the squamous intraepithelial lesion, which ultimately leads to invasive cervical cancer." (PMID 36245993, 2022). "Surprisingly, ERCC1 protein expression and the examined ERCC1 polymorphisms could not predict resistance to cisplatin based chemotherapy in this small metastatic or recurrent cervical cancer cohort." (PMID 28659181, 2017). "Specifically we tested whether ERCC1 expression and two frequently described SNPs (single nucleotide polymorphisms) ERCC1 (C8092A and N118 N) could predict response and clinical outcomes in metastatic or recurrent cervical cancer patients treated with cisplatin-based chemotherapy." (PMID 28659181, 2017). "For example, FTO overexpression in cervical cancer cells enhances chemo-radiation resistance, which correlates with decreased expression of the excision repair cross-complementation group 1 (ERCC1) protein, a crucial factor in nucleotide excision repair." (PMID 40485587, 2025). "Three in-vitro studies reported the molecular mechanisms of ERCC1 in cervical cancer that were available in the literatures." (PMID 36713431, 2022). "Based on the data from clinical and experimental studies, ERCC1 plays a key role in the progression of carcinoma of the uterine cervix and the therapeutic response of chemoradiotherapy." (PMID 36713431, 2022). "Overall, these results showed thatpatients with advanced cervical cancer who have a low level of ERCC1 have a worse OS and PFS." (PMID 36713431, 2022). "Therefore, based on the results of our meta-analysis and existing research reports, we believe that ERCC1 rs11615 polymorphism may reduce DNA repair ability by affecting its mRNA stability and protein expression level, leading to an increased risk of cervical cancer." (PMID 36245993, 2022). "In this present study, we summarize all published clinical and experimental data on ERCC1 applications in cervical cancer." (PMID 36713431, 2022). "It was reported that the 2-year OS of advanced cervical cancer patients in the low, intermediate, and high ERCC1 group was 68.6%, 71.7%, and 90.7%, respectively." (PMID 36713431, 2022). "The majority of the included studies (13/19, 68%) suggested that ERCC1 played a pro-oncogenic role in both early-stage and advanced cervical cancer." (PMID 36713431, 2022).
cervical carcinoma (continued). "First, in this review, the relationship between ERCC1 expression and the status of cisplatin-based treatments in early and advanced cervical cancer has been extensively studied." (PMID 36713431, 2022). "Excision repair cross-complementation group 1 (ERCC1) was found to be a promising biomarker of cervical cancer over the years." (PMID 36713431, 2022). "There were three experimental studies that investigated the aberrant expression of ERCC1 in cervix cancer." (PMID 36713431, 2022). "These preliminary studies indicated the prognosis and survival of patients with metastatic and recurrent uterine cervix cancer is poor when high ERCC1 expression is confirmed." (PMID 36713431, 2022). "In a previous study, a proteomic panel consisting of BCL-2, HER2, CD133, CAIX, and ERCC1 significantly predicted survival in patients with locally advanced cervical cancer." (PMID 34350111, 2021). "A significant correlation between ERCC1 mRNA expression levels and cisplatin resistance has been demonstrated in cervical cancer cell lines and several studies in patients with locally advanced cervical cancer have arrived at similar results." (PMID 34350111, 2021). "In the present study, we investigated the prognostic significance of BCL-2, HER2, CD133, CAIX, and ERCC1 expression in early-stage cervical cancer because they were prognostic factors in locally advanced cervical cancer." (PMID 34350111, 2021). "BCL-2, HER2, CD133, CAIX, and ERCC1 expression was determined by the immunohistochemical staining of 336 cervical cancer tissue microarrays." (PMID 34350111, 2021). "HER2, CAIX, and ERCC1 expression can be predictive protein markers for clinical outcomes in early cervical cancer patients treated primarily with radical surgery with or without adjuvant radiation." (PMID 34350111, 2021). "Worse DFS was also documented among 25 patients with FIGO IB – IIB cervical cancer who underwent either concurrent chemoradiotherapy with cisplatin or cisplatin-based chemotherapy and demonstrated high ERCC1 protein expression (P = 0.002)." (PMID 28659181, 2017). "ERCC1 expression proved to be a significant prognostic factor for survival in our metastatic or recurrent cervical cancer population treated with cisplatin based chemotherapy." (PMID 28659181, 2017). "The OS of ERCC1-low patients was also better than that of ERCC1-high patients, consistent with a finding from locally advanced cervical cancer patients undergoing cisplatin monotherapy." (PMID 29390553, 2017). "There are three other studies evaluated the relationship of ERCC1 status and the treatment response or survival of the patients with cervical carcinoma who received radiotherapy or chemoradiotherapy." (PMID 23259415, 2012). "This study showed that the upregulation of ERCC1 might be part of a radio-resistance mechanism in cervical cancer." (PMID 36713431, 2022). "ERCC1 has the opportunity to be a target for cervical cancer diagnosis or drug therapy." (PMID 36245993, 2022). "The present review highlights the crucial roles of ERCC1 expression in cervical cancer." (PMID 36713431, 2022). "Third, the exact and in-depth molecular mechanisms underlying the effects of ERCC1 expression and the development of cervical cancer are not clear due to limited studies and need to be further elucidated." (PMID 36713431, 2022). "The authors found that there was a significant correlation between ERCC1 mRNA expression and cisplatin resistance in all cervical carcinoma lines (all P< 0.05), but such an association was not significant in ERCC1 protein expression (all P>0.05)." (PMID 36713431, 2022). "According to the published data, high expression of ERCC1 might be correlated with poor prognosis in cervix cancer." (PMID 36713431, 2022).